IL6 (interleukin 6)
Diseases named in the same sentence as IL6 in open-access papers (continued):
Sharing a sentence is not in itself a finding about the gene and the disease.
infection (continued). "After 2 h of infection, the levels of IL-6 and TNF-α increased in the E. coli E44 group, when compared to the control group." (PMID 36289622, 2022). "CRP assists with the host response to infection, including phagocytosis, complement pathway, nitric oxide (NO) release, and cytokines production, especially interleukin-6 and tumor necrosis factor-α." (PMID 35154932, 2022). "For instance, infection of mouse bone marrow-derived macrophages (BMDM) with H. pylori stimulates the production of interleukin-6 (IL-6) and IL-1β via TLR2, IL-12, and IL-10 through the TLR4 pathways." (PMID 36317079, 2022). "polymorphum and S. gordonii promoted hGECs to secrete the proinflammatory factors TNF-α and IL-6 at 24 h of infection, while inhibiting the secretion of the anti-inflammatory factor TGF-β1." (PMID 35573793, 2022). "IL-6 is a major pro-inflammatory mediator that induces acute-phase responses and contributes to host defense against infection and tissue damage." (PMID 36496397, 2022). "In contrast, compared to pre infection, IL-6 concentration gradually increased during acute (1.08 ± 0.34 pg/mL) and chronic infection (3.59 ± 1.42 pg/mL)." (PMID 35281029, 2022). "The pro-inflammatory cytokine interleukin-6 (IL-6) is produced normally during infection or tissue damage and activates a cascade of pro-inflammatory signaling events during initial immune responses against pathogens but becomes overexpressed in CRS." (PMID 35892857, 2022). "Regression of serological infection indicators [such as interleukin-6 (IL-6), C-reactive protein (CRP), white blood cell count (WBC)] to the normal range was regarded as one of the diagnostic tests with high sensitivity to radical debridement." (PMID 36299571, 2022). "The combination of the levels of inflammatory factors, IL-6 and IL-18, at the 0-hour postoperative time point, significantly improved the predictive ability to the development of postoperative infection during perioperative period." (PMID 36299462, 2022). "The most pronounced increase after infection with HAdV26 was observed for IL-6, whose expression was increased 6 times in A549 cells and more than 15 times in SK-OV-3 cells." (PMID 35458402, 2022). "We examine the levels of TNF-α, IL-12, IFN-γ, IL-2, TGF-β, IL-10, IL-17, and IL-6 in lung lysates obtained from M. tb-infected mice at different timepoints post-infection." (PMID 35453358, 2022). "The mRNA levels of multiple pro-inflammatory cytokines, such as interleukin-1β (IL-1β), IL-6, tumor necrosis factor-α (TNF-α), and interferon-β (IFN-β), were up-regulated during the three PRV variants infection." (PMID 35458442, 2022). "(2014) reported a correlation between urinary levels of IL-6 with hematuria, heavy infection, and urinary tract pathology evaluated by ultrasonography." (PMID 36148227, 2022). "Although many potential biomarkers of infection have been studied, for example interleukin-6 (IL-6), interleukin-8 (IL-8), interferon gamma (TNF-α) and tumor necrosis factor alpha (TNF-β), satisfactory results have still not been obtained." (PMID 36670590, 2022). "We found that the levels of proinflammatory chemoattractant cytokines like IL-1α, MCP-1, and KC, as well as cytokines produced by macrophages and PMN in response to infection (IL-1 and IL-6), were increased in TBI/PAO1-infected mice." (PMID 35041620, 2022). "Ultimately, failure to adequately respond to IL-6 and IL-4 resulted in increased levels of M1 macrophage marker expression in vitro and exacerbated lung inflammation upon infection with Nippostrongylus brasiliensis in vivo." (PMID 34420044, 2022). "Similar to the findings of IL-6, the expression of arid5a was also significantly increased at 6 h after infection." (PMID 36059498, 2022). "Quantitative real-time PCR analysis of key inflammatory mediators demonstrated that SARS-CoV-2 (MA10) infection elevated cytokine IL-6 in BLAB/c and chemokine Ccl2 expression in Rag2−/− mice in comparison with mock-treated mice." (PMID 36680154, 2022).
infection (continued). "The association of mean levels of P-SEP, IL-6, PCT and CRP with the risk of infection at T0 was strong for P-SEP (p < 0.001) and CRP (p = 0.003) and weak for PCT (p = 0.214) and IL-6 (p = 0.088)." (PMID 36699313, 2022). "These responses are essential to fight and eliminate infection; therefore, IL-6 is essential for host defense." (PMID 35336914, 2022). "In most cases, an elevated IgM level is observed during infection, accompanied by elevated levels of IgG and the pro-inflammatory cytokine IL-6, and oxidation reactions take place in the cells." (PMID 36130989, 2022). "The steady-state IL-6 level in healthy people is about 1-10 pg/ml, however, its serum level is significantly elevated during infection, inflammatory disease, or cancer progression and is correlated with improper disease prognosis." (PMID 35463642, 2022). "During inflammatory response, IL-6, as a cytokine secreted following infection and stimulation, can promote the maturation and differentiation of T and B lymphocytes, mediate the acute inflammatory response, and enhance the chemokine effects." (PMID 35568847, 2022). "Previous studies have shown that mice that develop persistent bacteriuria have higher levels of the proinflammatory cytokines IL-5, IL-6, KC, and G-CSF in serum at 24 hpi compared to those that ultimately clear the infection." (PMID 35782131, 2022). "IL-6 is an inflammatory cytokine released in response to infection or tissue damage, triggering an inflammatory response from regulatory cells." (PMID 36059508, 2022). "Consistent with the transcriptional analysis, the level of TNF and IL-6 protein upregulation induced by infection was also significantly decreased in VS-X4 treated cells compared to controls cells." (PMID 35022513, 2022). "Consistent with this phenotype, concentrations of serum IL-6 (P = 0.03) were increased in older versus younger animals at pre-infection." (PMID 35039442, 2022). "Infection of NHPs with SUDV led to early and dramatic upregulation of transcripts encoding IP-10, IL-6, MCP-1, pro-inflammatory mediators that were previously reported to correlate with lethality in humans." (PMID 35657325, 2022). "Accordingly, an increase in cytokine transcripts (Il6, Il8, Il1a, Il1b, and Ifng) were observed in Jamaican fruit bats upon infection." (PMID 35215832, 2022). "Multiplexed detections of CRP, PCT, and IL-6 can fill in the blind area of single biomarker analysis and accurately diagnose the infection." (PMID 35144683, 2022). "All strains of Mmuc upregulated the proinflammatory cytokines TNF-α, IL-6, and IL-12p40 upon infection, and their levels increased in an MOI-dependent manner." (PMID 35269631, 2022). "IL-6 is a pleiotropic pro-inflammatory cytokine that is essential for resistance to TB after infection with high doses of intravenous Mtb." (PMID 35603194, 2022). "At 24 h, M. s_Rv1515c infection significantly (p < 0.01) suppressed the production of IL-6 (8-fold decrease) and IL-12 (2-fold decrease)." (PMID 35813825, 2022). "IL-6 is promptly and transiently produced in response to infections and tissue injuries and contributes to host defense via the stimulation of acute phase responses, hematopoiesis and immune reactions." (PMID 36560410, 2022). "Our results showed that the lower the level of Sirt3, the worse the indicators of inflammation (TNF-α, IL-6) and infection (PCT), a result that was expected." (PMID 35729330, 2022). "This study aims to quickly identify bacterial types through IL-6 and IL-10, select appropriate antibiotics in a timely manner, and understand the efficacy of anti-infection treatment through the trends of IL-6 and IL-10." (PMID 35432366, 2022). "The disappearance of inflammatory manifestations and regression of infection indicators (such as interleukin-6 (IL-6), C-reactive protein, white blood cell count) to the normal range were regarded as radical debridement." (PMID 36299571, 2022).
infection (continued). "The ex vivo infection of SFTSV in PBMCs from healthy donors demonstrated significantly high expression levels of IL-6, IL-1β, and IL-10 induced from clade IV in either PBMCs or supernatants that were tested at 24 h after inoculation." (PMID 35603493, 2022). "IL-6 and IL-1β treatment also significantly reduced expression of troponin T (by nearly 50%), and this was greatly enhanced by infection with SARS-CoV-2." (PMID 34669512, 2022). "After infection, cytokines IP-10, IL-6, and IL-8 were upregulated, while RANTES was downregulated, demonstrating a similar immune response found in vivo." (PMID 36071442, 2022). "When comparing the two strains, it was observed that IL-17RA-/- mice increased the concentration of IL-6 after infection (p = 0.0481)." (PMID 35844540, 2022). "IL-6 is a cytokine with pleiotropic functions, released by myeloid cells and involved in the acute immune response to infection, as well as in the pathogenesis of autoimmune disease." (PMID 35741174, 2022). "We found that HAdV26 infection of human epithelial cells triggers the expression of pro-inflammatory cytokines, namely IL-6, IL-8, IL-1β, and TNF-α." (PMID 35458402, 2022). "Both animal and human studies have shown that IL-6 can either influence an inflammatory or anti-inflammatory response to an infection." (PMID 35025927, 2022). "TLR4 constitutes one of the key players of the innate immune system, and is activated in response to an infection, resulting in NF-kB mediated production of pro-inflammatory cytokines, such as TNFα and IL-6." (PMID 36613673, 2022). "High levels of IL-6 contribute to the maintenance of infection because they possibly inhibit apoptosis of infected hepatocytes and control of the infection." (PMID 35336914, 2022). "IL-6 is also a recognized endogenous pyrogen involved in multiple acute-phase responses, such as infection, tissue damage, and hepatic protein synthesis." (PMID 36359365, 2022). "Instantaneously produced in reaction to infection and tissue damage, interleukin-6 (IL-6) contributes to host’s defense against emergent stress by activating acute phase and immune response." (PMID 36237426, 2022). "Severe infections with SARS-CoV-2 are strongly associated with a cytokine storm characterized by high levels of inflammatory cytokines, including IL-6 and TNF-α, in the plasma of patients." (PMID 35409421, 2022). "In contrast, we did find that the macrophage depletion at day one post N67C infection markedly decreased the IL‐6 serum levels of the sensitive strain (Mavs–/–) mice at day four post N67C infection." (PMID 35635376, 2022). "Physiologically, CRP is synthesized in the liver in response to stimulation of IL-6 increased by inflammation including infection." (PMID 36555941, 2022). "Infection with LV‐shRNA‐IL‐6‐induced marked suppression of IL‐6 mRNA in Capan‐1 compared to LV‐shRNA‐luciferase (mean RNAi rate at 24 h after transfection, 99%)." (PMID 35578571, 2022). "IL-6 is a pleiotropic cytokine that is involved in the acute immune response and inflammation to infection." (PMID 37065537, 2022). "Infection with SARS-CoV-2, a virus that has recently been linked to ALI and ARDS, has been linked to an inflammatory storm (marked by elevated levels of IL-6, IL-12, and IL-1, as well as TNF and deficient type I interferon activity)." (PMID 35813860, 2022). "Interleukin-6 (IL-6) is an inflammatory cytokine released by immune cells in response to stress, infection, or injury to induce inflammation as a defensive mechanism against further infection or trauma." (PMID 36551062, 2022). "Three upregulated cytokines, il-1b (18.09 ± 0.7539-fold change), il-6 (49.40 ± 1.641-fold change), and tnf-a (79.59 ± 6.921-fold change), indicated significant pulmonary inflammation levels post infection." (PMID 36249423, 2022). "Serum globulin mainly contains immunoglobulins, interleukin-6, and complements; it responds to infection and elevates with inflammatory reactions." (PMID 35915283, 2022).
infection (continued). "The important pro-inflammatory cytokines such as TNF-α (Tumour Necrosis Factor-α) and interleukins (IL), including IL-6 and IL-1, are critical players in the initial immune response against infection." (PMID 36298704, 2022). "IL-6 is rapidly produced in the process of internal trauma, surgery, stress response, infection, and other acute inflammatory reactions." (PMID 35549778, 2022). "Infection of F. nucleatum led to generation of IL-6 and TNF-α and they were inhibited by pretreatment with MAE significantly." (PMID 35564380, 2022). "HHV8-associated MCD is caused by uncontrolled infection with HHV8 leading to a cytokine storm driven primarily by excessive production of human interleukin-6 and viral interleukin-6." (PMID 35328266, 2022). "CRP is synthesized by the liver in response to any type of infection and is mainly stimulated by interleukin-6." (PMID 35566746, 2022). "IL-6 secretion remained elevated through six days post-infection in line with the expression results." (PMID 36128218, 2022). "Intensely and periodically produced in response to infection and tissue damage, interleukin 6 (IL-6) induces host defence by stimulating acute phase responses, hematopoiesis, and immune responses." (PMID 35805112, 2022). "In other words, the subset of patients that responded to the infection by secreting more elevated levels of IL-6 tended to show lower levels of serum Zn2+ ions." (PMID 36016660, 2022). "In the multivariable model, the highest OR of IL-6 levels for the occurrence of postoperative infection was found at POD2 (OR = 1.31, 95% confidence interval [CI] = 1.10-1.57, AUC = 0.8008)." (PMID 36299462, 2022). "Although replication kinetics and virus spread and of the two deletion mutants on CCB cells was undistinguishable from wild-type KHV-T (results not shown), differential expression was documented for nfκb, il6, il10 and il1b 48 h after infection." (PMID 36068296, 2022). "The severity of the infection was also assessed by analyzing the levels of inflammatory cytokines, including IL-1β and IL-6, in the BAL fluid of the lungs of A. baumannii-infected mice." (PMID 36431892, 2022). "Consistent with this, after AH1 infection, the levels of interleukin-6 (IL-6), tumor necrosis factor-alpha (TNF-α) and interleukin-1β (IL-1β) significantly increased in the lung tissues of p21˗/˗ mice compared with WT mice." (PMID 35180274, 2022). "Infection led to robust induction of chemokine and interleukin genes, including Il1b, Il6, Ccl2, Ccl3, Ccl4, Ccl7, Cxcl1, Cxcl2, Cxcl5, Cxcl9, and Cxcl10, and related receptor genes, including Ccr1, Ccr4, Ccr5, Ccr5, Ccr7, Cxcr2, Cxcr5, Il1r2, and Il1rn." (PMID 35487885, 2022). "T. denticola single species implant infections systemically increased IL-6, IL-13, CXCL1/KC, CCL-3/MIP1α, and CCL2/MCP compared to tissue infection without the implant." (PMID 35203495, 2022). "The heatmap highlighted interchangeable expression in immune related signaling (i.e., interleukin IL-6 signaling) at different time points after infection." (PMID 35269433, 2022). "This correlates with the results obtained in nonhuman primates, showing that the depletion of B-cells prior to infection results in a decrease in general lung IL-6 production." (PMID 35154093, 2022). "Several studies have shown disturbances in the natural IL-6:sIL-6R:sgp130 buffer in pathologies such as infections or CRS, type 2 diabetes, cardiovascular diseases, and in chronic inflammation such as experimental atherosclerosis." (PMID 35634332, 2022). "Meanwhile, the mRNA expression level of proinflammatory cytokines, IL-1β, IL-6, and TNF-α were remarkably reduced at 12–24 hpi after PR8 infection, which showed a high association with the decrease in β-TrCP." (PMID 36366524, 2022). "We found that serum levels of canonical proinflammatory cytokines interleukin-6 (IL-6), IL-8, tumor necrosis factor–α (TNFα), and IL-1β were similar when comparing infections with the two viruses." (PMID 35544568, 2022).
infection (continued). "The results of this experiment showed that infection of 3D4/2 cells with PCV2 at 8 or 36 h significantly upregulated the mRNA expression levels of inflammatory factors IL-6 and IL-8." (PMID 35624806, 2022). "As it induces inflammation, immune responses, and hematopoiesis, IL-6 plays a significant role in the acute host response to infection." (PMID 35982898, 2022). "IL-6 is a proinflammatory cytokine produced by M1 macrophages in normal response to infection and injury." (PMID 36358526, 2022). "In particular, we measured circulatory levels of interleukin-6 (IL-6), a pro-inflammatory cytokine observed in infection or inflammation." (PMID 36088364, 2022). "Further interrogation of the IL-6 signaling pathway showed that IL-6 signaling is enriched in monocytes in patients who survive infection, particularly at early time points." (PMID 35169146, 2022). "Cytokine gene expression in Caco-2 and RAW 294.7 cells in response to ST infection was quantified, with IL-2, IL-6, and TNF-α having been investigated." (PMID 35438052, 2022). "IL-6, released during infections or tissue injuries, is one of the main pro-inflammatory cytokines involved in the initiation and amplification of a cytokine storm." (PMID 35409421, 2022). "Following infection, AP stimulates the production of proinflammatory cytokines: IL-6, IL-8, IL-10, and TNF-alfa, which lead to recruitment of neutrophils, degranulation, and consequently tissue injury." (PMID 35889152, 2022). "After infection, production of IL-12p40, IL-6 and IL-10 was significantly reduced in AM compared to M1 and M2 macrophages while the production of TNFα was intact." (PMID 36776396, 2022). "Infection with N. caninum resulted in production of IL-6 in ascites and IFN-γ in ascites and sera at 5 dpi in both mouse strains (p < 0.05)." (PMID 36704563, 2022). "The primary role of TNF-α, IL-1β, and IL-6 is the regulation of inflammatory response when wounded, and during infection or immune stimulation." (PMID 35161266, 2022). "At 5 days post-infection, the levels of IL-6 detected in the lungs (p < 0.05) and BALF (p < 0.01) were significantly lower than those in the PBS + H9N2 group." (PMID 35847111, 2022). "BCGΔBCG1419c-elicited protection also associated with lower levels of proinflammatory cytokines (i.e. IL6, TNFα) at the site of infection in C57BL/6 mice." (PMID 35858977, 2022). "Comparing cytokine levels between patients with primary and secondary DENV infections, we observed that IL-2, IL-6, IL-31, and IL-12p70 were significantly higher in primary infection and MIP1β was significantly higher in secondary infection." (PMID 35631079, 2022). "This study found that following TTPB, there are significant changes in some inflammatory and infection biomarkers, namely uB2MG, IL-6, IL-8, IL-10 and TNF-α." (PMID 36154663, 2022). "IL-6 plays an important role in neutrophil-mediated inflammation and is activated in response to tissue injury and infection." (PMID 36145547, 2022). "The infection group showed a significant upregulation in IL-1β, IL-6, and CXCL2; the latter is homologous to IL-8 in mice (p < 0.05)." (PMID 35672331, 2022). "The alterations in mood and increase in fatigue after injections of IL-6 mirrors symptoms often reported during an infection." (PMID 36703956, 2022). "The infection resulted in a slight induction of IL-6, IP-10, IFNλ1, IFNλ2/3 and IFNβ protein secretion measured by flow cytometry of the supernatants of the epithelial chamber." (PMID 35805887, 2022). "The RANTES, IFN-α, MIP-1-α, and IFN-γ mRNA levels during reinfection were similar to the levels in the primary infection group; the levels of IL-6, IP-10, TNF-α, and IL-1-β were increased during reinfection but were lower than those during primary infection." (PMID 35893674, 2022). "Since the myofibrils are disorganized after infection, we determined the effects of infection on the contractile apparatus CM lines in the absence or presence of IL-6 and IL-1β." (PMID 34669512, 2022).